IDO1 (indoleamine 2,3-dioxygenase 1)
Diseases named in the same sentence as IDO1 in open-access papers (continued):
Sharing a sentence is not in itself a finding about the gene and the disease.
tumor (continued). "Besides, COX-2 and indoleamine 2, 3-dioxygenase 1 (IDO1) are considered “partners in crime” when it comes to the promotion of immune dysfunction and tumor survival in cancers." (PMID 32296574, 2020). "That said, IDO1 can be highly expressed by tumor cells themselves, and evidence that IDO1 expression by tumor DCs is a major mechanism of immune suppression is lacking." (PMID 32508825, 2020). "In vivo study revealed that knock-down of IDO1 and GBP1 inhibited tumor growth and metastasis." (PMID 33552086, 2020). "Indoleamine 2,3-dioxygenase 1 (IDO1) and tryptophan 2,3-dioxygenase (TDO) catalyze the rate-limiting step of tryptophan catabolism along the kynurenine pathway, which has important immuno suppressive properties, particularly in tumor cells and dendritic cells." (PMID 33363543, 2020). "Lastly, we assessed whether Ido1, which codes for IDO‐1, an immunoregulatory enzyme induced in macrophages by tumor‐derived factors, was induced by KPC‐conditioned media." (PMID 32039522, 2020). "Such drug combinations simultaneously kill tumor cells via immunogenic autophagy and in parallel opsonize tumor cells to checkpoint inhibitor immunotherapies via reduced expression of PD-L1, ODC and IDO1, and increased expression of Class I MHCA." (PMID 31885880, 2020). "Due to the observation of the trend of slowed tumor growth and the decreased Ki-67 expression in INCB-024350 treated SiHa xenograft tumors, we hypothesize that IDO1 expression contributes to the maintenance of cervical CSCs." (PMID 32545442, 2020). "Moreover, when combining miR-153-mediated IDO1 inhibition and chimeric antigen receptor (CAR) T cell therapy, further enhanced in vitro T cell killing activities and reduced xenograft tumor growth in mice were reported." (PMID 32722019, 2020). "In this regard, the lack of a statistically significant correlation between DFS and the high tumor expression of both IDO2 and IDO1 could appear to be a confounding result, in particular when compared to the OS analysis of the current series." (PMID 32536910, 2020). "To further extend these findings, we modeled a pro-inflammatory tumor microenvironment by exposing BrCa cell lines to the inflammatory cytokine IFN-γ, one of the most potent IDO1 inducers, at pathophysiologically relevant concentrations for up to 48 h and then assessed the effect on the KP profile." (PMID 33109232, 2020). "In current study, we found that the tumor IDO1 expression significantly increased after NCT, but did not change significantly after NCRT." (PMID 32733806, 2020). "Expression of IDO-1 in non-antigen-presenting cells, such as tumor cells, promotes the escape of the tumors from immunosurveillance." (PMID 33330446, 2020). "Our results demonstrate that tumor endothelial cells contribute to immunosuppressive feed-back loops in response to agonistic CD40 mAb therapy, which restrict the response to immunotherapy through IFNγ-driven expression of IDO1 that inhibits T-cell activation." (PMID 32231867, 2020). "Herein, we found that CD11b+ myeloid cells were enriched in IDO1 high-expressed but not in IDO1 low-expressed tumor area of HCC patients." (PMID 30777103, 2019). "These MØs express CD163 and M2-specific markers (increased expression of FOLR2 and MAF and reduced expression of ActA), and show an upregulated expression of different factors that favour tumour progression (including, among others, IL-10, TGF-β, IL-6, IL-8, IDO1, COX2 and GAL-1)." (PMID 31337120, 2019). "Given the expression of both IDO1 and TDO2 in tumours, inhibiting only IDO1 is unlikely to generate desirable clinical outcomes." (PMID 31795096, 2019). "Therefore, this study aimed to investigate the impact of IDO1 expression, PD-L1 expression, CD8+ tumor-infiltrating lymphocyte (TIL) status, and their combination on pathologic response and recurrence in EC patients who underwent neoadjuvant CRT." (PMID 30717285, 2019).
tumor (continued). "The rise in the Kyn/Trp ratio in cancer patients suggested an increase in IDO activity and low concentrations of tryptophan in serum/plasma is a reflection of the chronic activation of IDO-1 in the TME, which correlates with tumor progression and poor patient outcomes." (PMID 32039024, 2019). "Together, the IDO1 and IDO2 genes are variably upregulated in neoplastic cells as well as in stromal, endothelial, and innate immune cells of the tumor microenvironment and in tumor-draining lymph nodes." (PMID 30806743, 2019). "This is exemplified in the development of CDX-1401 which contains a DC receptor (DEC-205, CD205) specific monoclonal antibody to deliver the conjugated tumor antigen NY-ESO-1 in combination with TLR7/8 agonists, and is now in clinical trials combined with IDO1 inhibition (NCT02166905)." (PMID 31921140, 2019). "We demonstrated that stable IDO1 overexpression enhanced xenograft tumor growth in BALB/c mice but not in BALB/c nude mice." (PMID 31391111, 2019). "IDO-1 can be induced in immune cells recruited by the tumor, especially APCs through canonical and non-canonical pathways including NF-κB, Jak/STAT, PKC and TGF-β signaling pathways." (PMID 32039024, 2019). "IDO1 inhibitor 1-MT synergistically promoted the expression of IDO1 and antagonistically blocked the expression of TRAIL in IFN-primed AFMSCs, which resulted in the elimination of direct cytotoxicity of IFN-γ-primed AFMSCs to tumor cells." (PMID 31149015, 2019). "We previously demonstrated that immunosuppressive IDO1 is significantly increased in the normal healthy brain of 72–74 week old mice as compared with young 6–8 week old counterparts; independent of tumor burden." (PMID 30971917, 2019). "Moreover, tumor cells can evade the immune system or promote their own growth through increased EGFR expression and indoleamine 2,3-dioxygenase 1 or VEGF production." (PMID 31331053, 2019). "First, IDO1 expression, confirmed by either immunohistochemistry or polymerase chain reaction, in a tumor does not necessarily mean that this enzyme is functional." (PMID 30150994, 2018). "Nonetheless, IDO1 inhibition may still be important in the context of effects derived from antitumor vaccine, PD-L1 blockade, TGF-β sequestration, and/or tumor inflammation generated by ALT-803." (PMID 30227893, 2018). "Prior exposure of 4T1 tumors with [neratinib + valproate] significantly reduced the tumor expression of IDO-1 and ODC which was not altered in tumors also exposed to the anti-PD1 antibody." (PMID 29464055, 2018). "Across tumor types, this may create a situation in which activation and expansion of vaccine-derived T cells by ALT-803 may be especially relevant with IDO1 inhibition’s dampening of the inhibitory milieu within the TME." (PMID 30227893, 2018). "In tumor immune escape, IDO1 is a critically negative immunoregulatory factor, which induces the development, metastasis, and recurrence of tumors." (PMID 30314496, 2018). "Several inhibitors of IDO1 gene, a rate-limiting enzyme for the NAD+ de novo synthesis from tryptophan found to be downregulated in radiosensitive LABC tumours, have shown a radiosensitising effect in in pre-clinical studies, making it an attractive target for drug-radiation combination therapy." (PMID 30285791, 2018). "Furthermore, a survey of cancer cell lines indicated that 16% of tumour cell lines are IDO1 positive, while 19% are TDO positive and 15% express both TDO and IDO1." (PMID 28465467, 2017). "Negative factors that impact on both include tumour hypoxia, oxidative stress, tryptophan depletion due to high IFNγ-induced indoleamine 2,3-dioxygenase 1 (IDO1) levels and low pH." (PMID 29157300, 2017). "This study agrees with others where IDO1 expression was observed in the surrounding dendritic-like monocytes rather than the tumour cells." (PMID 26646699, 2016).
tumor (continued). "We therefore investigated it in a co-culture model in vitro: 3 tumor cell lines without constitutive IDO1 expression, including HepG2, SK-Hep-1 and Hep3B were co-cultured with peripheral blood mononuclear cells (PBMC)." (PMID 26895379, 2016). "The persistence of elevated inflammatory cytokines in the microenvironment may lead to chronic IDO1 expression in APC cells such as macrophages and DC and/or tumour cells thereby creating a pro-inflammatory feedback loop promoting tumour growth." (PMID 26646699, 2016). "Here we show indolamine-2,3-dioxygenase-1 (IDO1) expression, a kynurenine pathway enzyme, is increased not only in tumor cells but also in the microenvironment of human RCC compared to normal kidney tissues." (PMID 27572319, 2016). "Our present study showed that tumor cells cocultured with purified, untouched T cells failed to elevate IDO1 expression." (PMID 26895379, 2016). "More in general, IDO1-mediated TRP depletion establishes an immunosuppressive environment, amplifying tolerogenic antigen-presenting cells (APC), expanding Treg and downregulating cytotoxic T-cell activity, thus preventing immune response to tumor cells." (PMID 27174915, 2016). "To determine the impact of IDO on tumor growth, we confirmed that IDO1, not IDO2, was induced following tumor establishment in the lungs of both WT and IDO-deficient mice." (PMID 27705910, 2016). "In contrast, a subset of tumors expressed IDO1 within tumor cells in the absence of any inflammation." (PMID 25691885, 2015). "This is the case in endometrial carcinomas, which often contain IDO1-expressing tumor cells scattered within tumor nodules in the absence of obvious T-cell infiltration." (PMID 25691885, 2015). "Current trials do not select patients based on IDO1 expression in tumor tissue or assessment of systemic IDO1 activity by analysis of TRP and its metabolites in patients’ serum." (PMID 25628622, 2014). "Translated into the clinic, the non-genomic control of IDO1 by activated AhR becomes of great interest in neoplasia." (PMID 25360135, 2014). "The significant increase in both IDO-1 and IDO-2 expression in response to IFN-γ stimulation may suggest that both enzymes could contribute to tumor progression by inhibiting specific tumor immunity." (PMID 25415278, 2014). "Tumor cells and possibly specialized myeloid cells may express and catabolize TRP via TDO instead of or in addition to IDO1." (PMID 25628622, 2014). "Tumor and metastatic growth was enhanced in immunodeficient mice, confirming an intensified immune response in the absence of Ido1 expression." (PMID 22654951, 2012). "The prognostic value of IDO1 expression at the invasion front, but not in the central part of the tumour, further indicates that the invasion front indeed constitutes a biologically defined compartment." (PMID 22108515, 2012). "The relationship between IDO1-expressing tumours and T lymphocytes is, however, complex, as interferon-γ (IFN-γ), produced mainly by T lymphocytes in response to various immune stimuli, is a major inducer of IDO1." (PMID 22108515, 2012). "In contrast, IDO1 expression in the central part of the tumour did not exhibit any prognostic value or correlation with IDO1 expression at the tumour invasion front." (PMID 22108515, 2012). "Taking these factors into account, we identified higher IDO1 expression at the tumour invasion front as being an independent negative prognostic factor for pT1-4N1Mx-staged CRC." (PMID 22108515, 2012). "We used the Mouse Cell Cycle PCR Array from SABiosciences to compare cell cycle gene expression in two pairs of positive and negative Ido1 tumor cells." (PMID 22654951, 2012). "Both the IDO1 expression in the invasion front and in the centre of the tumour did not vary significantly across tumour stages (data not shown)." (PMID 22108515, 2012).
tumor (continued). "In this study, we demonstrated that higher IDO1 expression at the tumour invasion front correlates with progressive disease and impaired clinical outcome in a specific subset of patients with CRC, suggesting that IDO1 is an independent and reliable prognostic indicator for CRC." (PMID 22108515, 2012). "Indeed, the non-enzymatic function of IDO1 promotes a tolerogenic, long-term phenotype in dendritic cells, which are capable of sustaining an immunosuppressive environment around the tumor." (PMID 41262240, 2025). "Mechanically, with higher precise radiation dose, SRT may be more effective in inducing immunogenic cell death and remodeling tumor immune microenvironment, through powerful immune-modulatory pathways, such as cGAS/STING signaling, VEGF/VEGFR signaling, COX2/IDO1 signaling." (PMID 40748918, 2025). "Overexpression of IDO1 leads to increased production of KP metabolites in the local cancer microenvironment, and consequently activation of AHR, which results in initiation of tumorigenesis by suppressing antitumor immune responses and promoting tumor cell survival and motility." (PMID 40332338, 2025). "Additionally, indoleamine 2,3-dioxygenase 1 (IDO) expression in tumor cells facilitates the recruitment and activation of immunosuppressive myeloid-derived suppressor cells (MDSCs) to inhibit anti-tumor immunity." (PMID 41375050, 2025). "By contrast, IDO1 negative tumor cells mainly had a double negative or single positive status." (PMID 39962447, 2025). "Furthermore, IDO1 inhibition was found to synergize with radiation therapy and anti-PD-1 checkpoint blockade immunotherapy to increase survival in GBM only when IDO1 was inhibited on non-tumor cells." (PMID 40507361, 2025). "Indoleamine 2, 3-dioxygenase 1 (IDO1) is a rate-limiting enzyme that converts the essential amino acid tryptophan into downstream kynurenine (Kyn), indicated as a novel mechanism for blocking the proliferation and anti-tumor activity of immune cells by activating the aryl hydrocarbon receptor (AhR)." (PMID 39863603, 2025). "IDO1 activity suppresses T-cell activity by depleting tryptophan, which is required for Th1 and CD8+ T-cell-mediated immunity, while kynurenine binds to the aryl hydrocarbon receptor (AHR), which directly activates Treg differentiation and activity, resulting in reduced anti-tumor responses." (PMID 41235226, 2025). "Also PD-L1 status was not significantly correlated with IDO-1-positivity both in tumor and immune cells." (PMID 40475772, 2025). "In the tumor microenvironment, immunosuppressive myeloid cells upregulate amino acid-metabolizing enzymes, such as Arginase 1 (Arg1) and Indoleamine 2,3-dioxygenase 1 (IDO1), to deplete arginine and tryptophan—amino acids essential for T cell activation and function—thus promoting tumor progression." (PMID 39905317, 2025). "The observed co-expression of IDO2 and AhR, and the absence of associations between AhR and IDO1 or TDO2, may indicate a shift toward IDO2–AhR–driven immune suppression in advanced tumours." (PMID 40471422, 2025). "In conclusion, HMP1G NPs downregulated tumor‐derived IDO1 the AhR/STAT3/IL axis, improving KYN/TRP metabolism dysregulation, effectively overcoming metabolic immune suppression within the TME, reversing immunological tolerance in cold tumors, and sensitizing tumor cells to ICB therapy." (PMID 39661740, 2025). "Combining IDO1/TDO2 inhibitors with PD-1/PD-L1 inhibitors could be one of the most promising strategies for overcoming immune suppression by restoring T cell activity and reversing the immunosuppressive tumor microenvironment." (PMID 39997327, 2025). "While our study is based on immunohistochemical expression analysis, these findings support the hypothesis that IDO1 and IL4I1 may cooperatively influence the tumor immune microenvironment, possibly through metabolic reprogramming and immune evasion mechanisms." (PMID 40332319, 2025).
tumor (continued). "As TDO2 has also been shown to promote tumor growth in some cancers, it is reasonable to speculate that TDO2 and IDO2 may act as compensatory pathways to continue KYN production and influence tumor immunity when IDO1 is inhibited." (PMID 40103267, 2025). "It was found that the IDO1 inhibitor PF-06840003, when used in combination with anti-PD-L1, could induce a higher proportion of T cells secreting IFN-γ and the expression of the cytolytic enzyme granzyme A, thereby enhancing anti-tumor effects." (PMID 40861801, 2025). "It has been reported that IDO1 inhibitors do not destroy tumor cells directly." (PMID 40572474, 2025). "A catalytically inactive conformation of the IDO1 protein is increased by the inhibitors, through a mechanism that does not involve gene transcription and in a manner independent of their mechanism of inhibition and tumor type." (PMID 41262240, 2025). "After IDO1 silencing, TDO2 may function as a compensatory mechanism to sustain tumor growth." (PMID 40103267, 2025). "The non-enzymatic activity of IDO1 enhances tumor progression." (PMID 40137109, 2025). "Notably, USP14 knockdown upregulates cytotoxic T-cell activity and enhances anti-tumor immunity in CRC by downregulating IDO1 expression without affecting AhR activity, suggesting a potential avenue for CRC-targeted therapy." (PMID 38462620, 2024). "Although this may partially be compensated for by the considerably higher AhR-activating potency of indole-3-pyruvic acid compared to IDO1-generated metabolites, it remains unclear whether IL4I1 is capable of achieving significant AhR activation in most tumor types." (PMID 39211039, 2024). "Moreover, although a limited body of studies have revealed the effects of T cell and embryonic stem cell‐expressed IDO1 on glucose metabolism, these studies have not delved into the influence of IDO1 on glucose metabolism specifically within the tumor setting." (PMID 38706741, 2024). "Based on the fact that several tumor suppressive proteins (IDO1, VISTA, TIM-3, LAG-3 and ICOS) had a higher expression in the tumor-sparse region, we conclude that a wide range of T-cell suppressive features may hamper the expansion of T cells in regions also adjacent to the tumor." (PMID 39001353, 2024). "Most trials evaluating IDO1 inhibitors or modulators have not paid attention to IDO1 expression; it is therefore of potential interest that high IDO1 expression differs from patient to patient between and within tumor types." (PMID 38632994, 2024). "Of potential relevance, recent data suggest that the upregulation of IDO1 could be driven by tumor-infiltrating CD8+ T cells, which in turn suggests that IDO1 expression may be induced in the presence of a pre-existing “hot” environment, which makes ICIs more effective." (PMID 38632994, 2024). "In summary, the differential expression of IDO1 was closely related to tumor immunity and may serve as a novel target for immunotherapy and prognostic markers." (PMID 38539263, 2024). "In detail, the IDO1-negative tumors had significantly higher mitotic counts, higher histologic grades and scores, and reduced ER-α or PR scores than the IDO1-positive tumors with 11–100% positive tumor cells." (PMID 39061522, 2024). "However, despite preclinical evidence supporting the efficacy of IDO1 inhibition in tumor suppression, recent clinical trials have not mirrored these outcomes." (PMID 38816360, 2024). "Nevertheless, the combination blockade of IDO1 and PD‐1/PD‐L1 might be more appropriate for inflamed tumors, given that the driving factor for IDO1 expression in NSCLC patients is likely inflammation rather than the tumor itself." (PMID 38469550, 2024). "Furthermore, an analysis utilizing the TSIDB database uncovered a significant correlation between AEG-1 and several key factors, including the tumor-promoting cell Th2, immune activator IL6, CXCR4, immunosuppressants CTLA4, IL1, IDO1, LAG3, PDCD1, TGFB1, and the DHC molecule HLA-DPA1." (PMID 39483471, 2024).